TBC1D8B (TBC1 domain family member 8B)
Description:
Involved in vesicular recycling, probably as a RAB11B GTPase-activating protein.
Synonyms: FLJ20298; RP11-321G1.1; GRAMD8B; NPHS20
Tractability: PROTAC: ubiquitination databases record sites on it; its protein half-life has been measured.
Gene: Protein-coding gene on chromosome X (106,802,673 to 106,876,150, forward strand). Ensembl gene ENSG00000133138.
Subcellular location: Cytoplasm, cytosol
Subcellular location (Human Protein Atlas): Cytosol
Pathways (Reactome):
Vesicle-mediated transport: Golgi Associated Vesicle Biogenesis
Gene Ontology:
Molecular function: protein binding; GTPase activator activity; calcium ion binding
Biological process: glomerular filtration; vesicle-mediated transport
Cellular component: cytosol
Gene-disease validity (ClinGen):
ClinGen rates the evidence that TBC1D8B causes each of these diseases.
nephrotic syndrome, type 20 (X-linked): Moderate.
Homologues: Orthologues: chimpanzee TBC1D8B (99% identical), macaque TBC1D8B (97% identical), pig TBC1D8B (94% identical), rabbit TBC1D8B (93% identical), dog TBC1D8B (91% identical), mouse Tbc1d8b (91% identical), rat Tbc1d8b (90% identical), guinea pig TBC1D8B (88% identical), tropical clawed frog tbc1d8b (71% identical), zebrafish tbc1d8b (63% identical). Paralogues in human: TBC1D8 (53% identical), TBC1D9 (52% identical), TBC1D9B (52% identical), SGSM3 (15% identical), RABGAP1 (14% identical), RABGAP1L (14% identical), TBCK (12% identical), TBC1D2B (12% identical), TBC1D2 (12% identical), TBC1D1 (11% identical), TBC1D4 (11% identical), EVI5L (11% identical), and 33 more.
Diseases named in the same sentence as TBC1D8B in open-access papers:
TBC1D8B is named in the same sentence as 11 diseases in open-access papers, as found by Europe PMC text mining. Sharing a sentence is not in itself a finding about the gene and the disease. The quoted sentences say what the papers report.
melanoma (2 papers, 2020 to 2022). A malignant, usually aggressive tumor composed of atypical, neoplastic melanocytes. "Seven prognosis associated TBCs genes including TBC1D13, TBC1D16, TBC1D7, TBC1D10C, TBC1D19, TBC1D8B, and TBC1D15 were identified in melanoma." (PMID 33194704, 2020).
nephrotic syndrome (2 papers, 2020 to 2022). A collection of symptoms that include severe edema, proteinuria, and hypoalbuminemia; it is indicative of renal dysfunction. "Interference of TBC1D8B increased basal autophagy and exocytosis through inhibiting the expression of RAB11 which plays a crucial role in the pathogenesis of nephrotic syndrome." (PMID 33194704, 2020).
TBC1D8B also shares sentences with these, for which no sentence is quoted: ciliopathies (1 paper); cystic kidney disease (1); deafness (1); DOORS syndrome (1); Epileptic encephalopathy (1); kidney (1); myoclonic epilepsy (1); neurological disorders (1); onychodystrophy (1).